TERT (telomerase reverse transcriptase)
Diseases named in the same sentence as TERT in open-access papers (continued):
Sharing a sentence is not in itself a finding about the gene and the disease.
leukemia (22 papers, 2013 to 2024). A malignant (clonal) hematologic disorder, involving hematopoietic stem cells and characterized by the presence of primitive or atypical myeloid or lymphoid cells in the bone marrow and the blood. "Across 1019 samples previously profiled with deep RNAseq, we found that hematopoietic cell lines (leukemias, lymphomas, and myelomas) were associated with the greatest mean expression of TERT (p = 5.8×10−26, two-sided Mann-Whitney U test)." (PMID 34486523, 2021). "The occurrence of telomere shortening in leukaemias depends particularly on telomerase activity, telomerase reverse transcriptase catalytic subunit (TERT) expression, TERT promoter gene mutation (TERTp), and variability within the TERT gene." (PMID 34857839, 2021). "It is interesting to note that TERT dysregulation leads to disease development as previous studies in other types of leukemia associates this with chemo-resistance, disease progression, and poor prognosis." (PMID 34440361, 2021). "Moreover, G0/G1 phase arrest in HL-60 (leukemia) is also associated with a decrement of telomerase activity as well as TERT and TERC levels." (PMID 33450878, 2021). "All these findings designate TERT as ideal tumour-associated antigen (TAA) that could be exploited to design a selective cancer immunotherapy for the treatment of leukemias." (PMID 29152058, 2017). "Knocking out TERC in mouse can induce cell cycle arrest and apoptosis of leukemia stem cells, while knocking down TERT in AML cells isolated from leukemia patients can gain similar results." (PMID 38111043, 2023). "Dysregulated TERT activity was described as one of the many essential factors for leukemia emergence, and it has been depicted as a common alteration in leukemogenesis." (PMID 36354684, 2022). "This would include detailed information on the transcriptional and translational regulation of TERT, the dysregulation of TERT in leukemias, and the clinical implications of this gene in the treatment of these disorders." (PMID 34440361, 2021). "In specific cancer types such as CNS, lung, and leukemia, we found a higher correlation between TERT mRNA expression and telomere content." (PMID 34486523, 2021). "Recent research has indicated that targeting of this gene is able to control the survival of malignant cells and therefore offers a potential treatment for TERT-dependent leukemias." (PMID 34440361, 2021). "All major forms of leukemia including acute myeloid (AML), acute lymphoid (ALL), chronic myeloid (CML), and chronic lymphoid (CLL) leukemia have implicated TERT as an essential factor for the development and progression of the disease." (PMID 34440361, 2021). "We find that telomerase reverse transcriptase (TERT) expression correlates with telomere content in lung, central nervous system, and leukemia cell lines." (PMID 34486523, 2021). "TERT dysregulation that has been identified as one of the contributors to the pathogenesis of leukemia and has been reported in both AML and ALL." (PMID 34440361, 2021). "As in the case of most leukemia, TERT activation occurs via STAT5 mediated binding and its phosphorylation state." (PMID 34440361, 2021). "The mediators involved in the dysregulation of TERT have been extensively studied and the mapping of their contribution to pathological pathways have been reported in the various forms of leukemia as well." (PMID 34440361, 2021). "The prevalence of TERT dysregulation remains to be determined in each subtype of leukemia and is also highly dependent on the population and recruitment criteria of each study." (PMID 34440361, 2021). "The anti-TERT based immunotherapy significantly controlled tumour progression improving the survival of leukaemia-bearing mice." (PMID 29152058, 2017). "Together, our findings demonstrate that TERT-based adoptive cell therapy is a concrete platform of T cell-mediated immunotherapy for leukaemia treatment." (PMID 29152058, 2017).
leukemia (continued). "It has been reported that the treatment of SMA results in the downregulation of TERT transcript in leukemia cells." (PMID 30460075, 2017). "In the absence of telomerase-independent alternative lengthening of telomeres, only blasts with TERT expression should possess the ability for long-term leukaemia propagation." (PMID 23229821, 2013). "Furthermore, in terms of DNA methylation status it was found that methylation of TERT promoter was crucial in different stages of leukemia development as it confers different functional advantages." (PMID 34440361, 2021). "Thus, the findings provide a new platform of TERT-based adoptive T cell therapy for leukemia with overexpression of TERT, particularly for patients who are unable to receive HSCT." (PMID 30622438, 2019). "TERT is overexpressed in greater than 80% of primary tumors and leukemia cells." (PMID 30622438, 2019). "Since TERT deregulation is a common step in leukaemia, treatments targeting telomerase might be useful for the therapy of hematologic malignancies." (PMID 29152058, 2017). "Other immune-evasion mechanisms, such as antigen loss or antigen presentation deficiency, seem not to play a critical role in our experimental setting since residual leukemia cells in TERT-treated mice maintained telomerase expression and HLA-A2 molecules (data not shown)." (PMID 29152058, 2017). "Our results are in agreement with previous findings obtained in leukemia cell lines suggesting that epigenetic mechanism can be responsible of different ATRA response and highlights that a low methylation level of TERT promoter correlates with drug efficacy." (PMID 31291979, 2019). "We emphasize the word “apparent” since it also became clear that there is no single pattern concerning telomere and telomerase functions in leukemia, especially considering all possibilities of non-canonical actions of TERT." (PMID 36980962, 2023).
acute myeloid leukemia (21 papers, 2009 to 2025). Acute myeloid leukemia (AML) is a group of neoplasms arising from precursor cells committed to the myeloid cell-line differentiation. "This is the case of TERT p.P65T variants since the p.P65A variant has been found in patients of acute myeloblastic leukemia (AML)." (PMID 30995915, 2019). "We recently found an increased rate of constitutional TERT hypomorphic mutations in patients with acute myeloid leukemia." (PMID 19936245, 2009). "A heterogeneous loss-of-function TERT K570N or TERT S368F mutation in two large families, through autosomal dominant inheritance, was previously reported that presented a range of hematologic manifestations from macrocytosis to acute myeloid leukemia and severe liver disease." (PMID 39849589, 2025). "The aim of this study was to investigate the association between telomerase reverse transcriptase (TERT) gene polymorphisms and acute myeloid leukemia (AML) susceptibility in a Chinese Han population." (PMID 32694935, 2020). "Previously, we found that most patients with acute myeloid leukemia (AML) expressed at least one of the leukemic associated antigens (LAAs) WT1, survivin and TERT, and different combinations of the three LAAs predicted negative clinical outcomes." (PMID 28477011, 2017). "Among acute myeloid leukemia patients without TERT promoter mutations, T349C carriers had significantly shorter survival times." (PMID 29100407, 2017). "Here we analyzed TERT and protection of telomeres 1 gene (POT1) mutations, and four different TERT SNVs in 226 acute myeloid leukemia (AML) patients and 806 healthy individuals in a case referent design, where also overall survival was assessed." (PMID 26298771, 2015). "Previous studies showed that triptonide induces cellular senescence and apoptosis by suppressing transcription of TERT and oncogenic c-MYC in acute myeloid leukemia cells." (PMID 33510281, 2021). "Additionally, inherited changes in telomere length as a result of mutations in the telomere maintenance genes TERT and TERC have been identified in four HM families with myelodysplastic syndrome and acute myeloid leukemia (MDS-AML)." (PMID 25351806, 2015).
bladder tumor (20 papers, 2014 to 2025). "Somatic mutations in the TERT promoter (−124C > T and −146C > T) are detected in ∼65 % of bladder tumors across all stages." (PMID 40698358, 2025). "Conversely, somatic mutations in the TERT promoter, especially the −124C > T and −146C > T hotspots, are highly prevalent across all stages and grades of bladder tumors and have emerged as strong prognostic indicators." (PMID 40698358, 2025). "The relationship between mutations in the TERT promoter and recurrence of bladder tumors was assessed using the Kaplan-Meier survival analysis." (PMID 40995307, 2025). "The TERT (Telomerase Reverse Transcriptase) gene promoter mutation is one of the most prevalent mutations in urothelial bladder tumors and this mutation is related to bladder tumor progression." (PMID 38666908, 2024). "Our aim was to estimate the prevalence of TERT core promoter mutations in young patients with bladder tumor (first diagnosis at 40 years of age or younger) and to assess the differences in clinical tumor characteristics and disease progression." (PMID 38666908, 2024). "In the context of a bladder neoplasm, detection of TERT promoter mutation has emerged as a surrogate marker for urothelial origin." (PMID 38833173, 2024). "On the other hand, four out of nine analyzed whole-organ mapping bladder tumors were monoclonal for TERT promoter mutations pointing to the fact of a possible seeding or migration of the cells." (PMID 33562516, 2021). "Frequency of TERT promoter mutation in different types of bladder tumor, including those with rare variant histology." (PMID 34395278, 2021). "MAF of the TERT C228T mutation in urinary cfDNA before TURBT was an independent factor associated with bladder tumor recurrence after adjustment for European Organization for Research and Treatment of Cancer (EORTC) recurrence score and age." (PMID 32509577, 2020). "Patients in the surveillance group with the TERT C228T mutation had significantly worse prognosis for bladder tumor recurrence (p = 0.0006)." (PMID 32509577, 2020). "The mutant allele frequency of TERT C228T in urinary cfDNA before TURBT was significantly associated with bladder tumor recurrence." (PMID 32509577, 2020). "The co-existence of multiple sub-clonal populations, including multiple TERT mutated clones has been also reported in bladder tumors." (PMID 33260905, 2020). "In this study, we evaluated TERT promoter mutations in PDD false-positive samples in patients with non-muscle-invasive bladder cancer (NMIBC) who underwent PDD-assisted transurethral resection of bladder tumor (PDD-TURBT) after oral 5-ALA administration." (PMID 40995307, 2025). "The presence of the TERT c.-124C > T mutation in muscle-invasive bladder tumor could be considered a biomarker of tumor aggressivity." (PMID 35713686, 2022). "Similarly, a high MAF of TERT c.-124C>T in urinary ctDNA was found to be associated with bladder tumor recurrence." (PMID 36233035, 2022). "Additionally, we reported that TERT C228T mutation in urinary cfDNA was associated with bladder tumor recurrence after transurethral surgery for NMIBC or radical nephroureterectomy for UTUC." (PMID 34395278, 2021). "Therefore, we analyzed TERT mutations at different known promoter nucleotide positions using a large cohort of whole-organ mapping bladder tumors." (PMID 33562516, 2021). "Of the two-thirds of bladder tumors carrying a TERT promoter mutation, Rachakonda P.S. and colleagues observed that the C228T mutation (G > A) was the most frequent change in BC followed by the C250T mutation, identified in 53.5% and 11.6% of all tumors, respectively." (PMID 32839402, 2020). "In addition, patients with high TERT C228T allele frequency (≥14%) had significantly worse prognosis in bladder tumor recurrence than patients with low TERT C228T allele frequency or negative TERT C228T (p = 0.0322)." (PMID 32509577, 2020).
bladder tumor (continued). "Of the 6 patients who experienced bladder tumor recurrence during the follow-up period, one had tested positive by UroVysion, and four patients tested positive for TERT C228T." (PMID 32509577, 2020). "Mutations in human TERT, FGFR3, PIK3CA, and RAS genes have been proposed as potential molecular markers in bladder tumor." (PMID 27611947, 2016). "We have previously shown that the presence of TERT promoter mutations in non-cancerous urothelium was significantly linked to the recurrence of bladder tumors within the bladder following TURBT." (PMID 40995307, 2025). "TERT promoter mutations have been identified in the vast majority of bladder tumors independent of pathological characteristics." (PMID 33562516, 2021). "Thus, TERT C228T mutation was detected in NMU, which was a reliable independent prognostic factor of bladder tumor recurrence." (PMID 32533903, 2020). "In the post-surgical surveillance group, patients positive for the TERT C228T mutation had significantly worse prognosis for bladder tumor recurrence than mutation negative patients (p < 0.001)." (PMID 32509577, 2020). "Among all 11 cases of SCC of the urinary bladder evaluated for TERT promoter mutation, 2 were radical cystectomy, 2 were transurethral resections of bladder tumor (TURBT), 5 were bladder tumor biopsy and 1 was with both partial cystectomies and metastatic biopsy from liver." (PMID 25042800, 2014). "We demonstrated that the TERT C228T mutation was significantly associated with bladder tumor recurrence in the surveillance group, and that ≥14% MAF of TERT C228T, and not just a positive for TERT C228T, was associated with bladder tumor recurrence in pre-TURBT group 1." (PMID 32509577, 2020).
medulloblastoma (20 papers, 2013 to 2025). A malignant, invasive embryonal neoplasm arising from the cerebellum. "Our patient had additional mutations at POLE, LYST, KMT2D, and TERT, all of which have been shown to significantly reduce overall survival in medulloblastoma." (PMID 40958970, 2025). "As far as we know, one study in medulloblastoma reported a TaqMan-based genotyping assay to detect recurrent TERT promoter mutations." (PMID 33776938, 2021). "In this study, we report the clinical and mutational profiles of 99 adult medulloblastomas, investigated for molecular group, coding mutations, TERT promoter mutations, MYC and MYCN amplifications, and survival outcome." (PMID 33172502, 2020). "The strong enrichment of TERT promoter mutations in adult SHH medulloblastomas has been reported by multiple studies." (PMID 33172502, 2020). "Recent studies have reported frequent Telomerase Reverse Transcriptase (TERT) promoter mutations in medulloblastomas: in fact, TERT mutations were identified in 21% of medulloblastomas." (PMID 30279357, 2018). "Telomerase reverse transcriptase (TERT) promoter mutations were recently shown to drive telomerase activity in various cancer types, including medulloblastoma." (PMID 24174164, 2013). "TERT promoter mutations are the most common recurrent somatic point mutation in medulloblastoma, and are very highly enriched in adult SHH and WNT tumors." (PMID 24174164, 2013). "TERT mutations define a subset of SHH medulloblastoma with distinct demographics, cytogenetics, and outcomes." (PMID 24174164, 2013). "In this study, we analyzed a representative set of 466 medulloblastomas for TERT promoter mutations." (PMID 24174164, 2013). "Based on the transcriptional heterogeneity of SHH tumors in infant and adult patients, we suspect that the adult cluster mainly comprised TERT-mutated medulloblastomas." (PMID 24174164, 2013). "Overall, TERT promoter mutations were identified in 21 % of medulloblastomas." (PMID 24174164, 2013). "Interestingly, we found that TERT-mutated medulloblastomas present less frequently with metastatic dissemination at diagnosis compared to TERT wild-type tumors (p = 0.03)." (PMID 24174164, 2013). "A total of 21 % of medulloblastomas harbored TERT mutations." (PMID 24174164, 2013). "In pediatric tumors, changes in PR Set Region 6 (PRDM-6) in a subset of medulloblastomas (MBLs) and in the Telomerase Reverse Transcriptase (TERT) gene in NB were detected via sequencing analysis." (PMID 41009448, 2025). "We performed molecular grouping, targeted sequencing, and TERT promoter Sanger sequencing on a cohort of 99 adult medulloblastomas." (PMID 33172502, 2020). "Strikingly, the highest frequencies of TERT mutations were observed in SHH (83 %; 55/66) and WNT (31 %; 4/13) medulloblastomas derived from adult patients." (PMID 24174164, 2013). "Both of these cases with TERT amplification were SHH-driven medulloblastomas with wild-type TERT status, which were derived from pediatric patients who were both alive after 15 and 83 months of follow-up." (PMID 24174164, 2013). "We detected several enhancer-hijacking events, an ecDNA containing the MYCN gene, and rare structural rearrangements, such a chromothripsis in a G4 medulloblastoma, chromoplexy involving 8 different chromosomes, a TERT gene rearrangement, and a PRDM6 duplication." (PMID 37576901, 2023). "TERT mutations are recurrent in the WNT subgroup of medulloblastoma although they do not impact prognosis." (PMID 34439356, 2021). "The highest frequencies of TERT mutations are observed among SHH (83%) and WNT medulloblastomas." (PMID 30279357, 2018). "We analyzed the TERT promoter by direct sequencing and genotyping in 466 medulloblastomas." (PMID 24174164, 2013). "The initial analyses of TERT mutations in medulloblastoma mainly catalogued the mutational frequency rather than correlating the molecular and clinical features of these mutations in a subgroup-specific manner." (PMID 24174164, 2013).